EGFR (epidermal growth factor receptor)
Diseases named in the same sentence as EGFR in open-access papers (continued):
Sharing a sentence is not in itself a finding about the gene and the disease.
tumor (continued). "Of these, seven patients underwent post-surgical intervention with CART- EGFR vIII and were found to have metastasized CART-EGFR vIII cells to tumor cell areas." (PMID 37190280, 2023). "Crosstalk between tumor cells and fibroblasts has been investigated in vitro and in vivo as a potential therapeutic target and source of EGFR TKI resistance." (PMID 36647832, 2023). "Phage display technology has been used to identify high-affinity peptides and antibodies that can bind to EGFR and inhibit its signaling pathway, leading to the inhibition of tumor cell proliferation and survival." (PMID 37243023, 2023). "It was observed by immunohistochemistry (IHC) that almost all cells within the tumor express high levels of EGFR protein." (PMID 37446288, 2023). "AFM24 is a tetravalent bispecific innate cell engager targeting EGFR on tumor cells and CD16A on natural killer cells to enhance antitumor antibody-dependent cellular cytotoxicity." (PMID 38107063, 2023). "Osimertinib inhibits the EGFR pathway and also induces tumor cells to produce Reactive oxygen species (ROS), promoting the protective autophagy of the LUAD cells, thereby activating the bypass pathways." (PMID 37596251, 2023). "We next examined the individual genes contributing to the relationship between increased tumor-stroma interaction and EGFR TKI resistance." (PMID 36647832, 2023). "The propagation of many known human neoplasms are driven by activation of epidermal growth factor receptor (EGFR) and its subsequential signaling pathways." (PMID 37409250, 2023). "Several research groups have exploited the targeting of EGFR using specific peptide ligands selected by phage display in different tumor contexts." (PMID 37048151, 2023). "There is a positive correlation between arsenic concentrations in human toenails and the amount of EGFR protein present in NSCLC tumor samples." (PMID 36831545, 2023). "In this work, we have engineered EGFR‐specific NKCEs triggering NKp46‐mediated tumor cell eradication by employing camelid‐derived single domain antibodies (sdAbs)." (PMID 36775946, 2023). "Liquid biopsy via circulating tumor DNA (ctDNA) has developed with its high accordance to tissue testing in determining EGFR status." (PMID 36870951, 2023). "CAR-NK is particularly effective at inducing the recognition and lysis of tumor cells that overexpress EGFR on various tumor cell surfaces, such as breast, lung, and carcinoma." (PMID 37349810, 2023). "False negative predictions by the thresholding method were found in tumor tissues with low or heterogeneous expression of EGFR (i.e., tumor necrosis in the interior of ROIs)." (PMID 36875185, 2023). "In clinical practice, although tumor shrinkage is observed with EGFR-TKIs, complete radiologic tumor disappearance is incredibly rare, and in most cases, residual radiologic disease remains." (PMID 36835536, 2023). "The overactivation of EGFR contributes to cancer malignancy via promoting proliferation, migration as well as survival of the tumor cells." (PMID 37919290, 2023). "They found EGFR inhibitors suppress tumor progression through micropinocytosis-mediated TEXs internalization." (PMID 36768288, 2023). "These EVs stimulate the EGFR on tumor cells in an autocrine/paracrine manner and enhance the motility and invasiveness of tumor cells." (PMID 36674900, 2023). "Epidermal growth factor receptor (EGFR), a member of the tyrosine kinase receptor family, is closely associated with tumor angiogenesis, cell proliferation, invasion, metastasis, and inhibition of apoptosis." (PMID 37795033, 2023). "The PANAMutyper R EGFR test showed an analytical sensitivity of 1% during the analysis of the corresponding tumor tissue samples." (PMID 37372399, 2023). "Activation of tumor cell autophagy by EGFR-TKI is a potential key mechanism for obtaining drug resistance." (PMID 37596251, 2023).
tumor (continued). "EGF was demonstrated to be antiapoptotic in tumor cells excessively expressing EGFR, a condition observed in the vast majority of solid tumors." (PMID 38090376, 2023). "The impact of tumor cell enrichment and increasing sample input on the performance of IdyllaTM EGFR assay." (PMID 37064089, 2023). "One of the first studies on NPs was published in 2011 and focused on the usage of EGFR-targeted heparin-cis-diamminedichloroplatinum (II) (EHDDP) NPs for the delivery of ChT to the tumor site in NSCLC." (PMID 37754880, 2023). "This was also reflected in our results, which identified the second highest number of recommended drugs for patients with tumours harbouring EGFR amplification." (PMID 36670542, 2023). "To explore the inhibitory effect of FYLM on tumor progression in vivo, we first constructed a xenograft mouse model harboring EGFR-Del19/T790M/C797S-mutant via subcutaneously inoculating LLC-triple mutant cells into C57BL/6J mice." (PMID 36744262, 2023). "More importantly, we found that the combination of JAC4 and osimertinib synergistically inhibited the tumor-bearing growth and metastasis of EGFR-mutant LUAD cells in vivo compared with AZD9291 alone." (PMID 37240137, 2023). "CL-387,785 is an irreversible selective EGFR inhibitor designed to specifically inhibit EGFR autophosphorylation and tumor cell proliferation." (PMID 37601068, 2023). "The correct re-characterization of the tumor is therefore crucial for initiating subsequent therapy for NSCLC patients who progressed under EGFR-TKI therapy." (PMID 37444638, 2023). "Bispecific antibodies can enhance the binding of EGFR and nanobodies, guide the recruitment of T cells to the antibody, and have a stronger therapeutic effect to inhibit tumor cell proliferation." (PMID 36835588, 2023). "On the other hand, the tumor microenvironment also plays a role in conferring extrinsic resistance to anti-EGFR therapy." (PMID 36979659, 2023). "First-generation EGFR-directed tyrosine kinase inhibitors (EGFR-TKI) are limited by blood-brain barrier penetration and T790M tumor mutations, wherein third-generation EGFR-TKIs, like Osimertinib, have shown greater activity." (PMID 37190312, 2023). "EGFR immunoreactivity in IDH1mt tumours was also observed in past, although these usually do not usually harbour EGFR amplification." (PMID 37568909, 2023). "Bags predicted to be EGFR mutant had a lower standard deviation of tumor nuclei fraction across the highest-attention patches (p = 0.028, Pearson’s r: − 0.317)." (PMID 36927889, 2023). "TKIs bind to the tyrosine kinase domain of EGFR and block EGFR-driven signaling downstream to exert their tumor-inhibitory effects." (PMID 37301856, 2023). "Vascular endothelial growth factor (VEGF) and the epidermal growth factor receptor (EGFR) are complementary pathways that play a fundamental role in tumor survival and diffusion." (PMID 37834474, 2023). "We identified 121 primary and 147 recurrent tumours, 20 of which were EGFR-amplified in each group, with both copy number and RNA profiled." (PMID 36765632, 2023). "At the protein level, co-expression of VEGFR2 and other receptor tyrosin kinases (RTKs) such as EGFR and MET, expressed on endothelial and tumor cells, respectively, has been associated to aberrant VEGF-A expression and intrinsic resistance to BEVA." (PMID 37041632, 2023). "More than 60% of NSCLCs express epidermal growth factor receptor (EGFR), making it an important therapeutic target for these tumours." (PMID 38087217, 2023). "Cetuximab, the monoclonal antibody targeting the extracellular domain of EGFR, has shown its great efficacy in the promotion of apoptosis and the inhibition of tumor cells-like characteristics in numerous cancers." (PMID 36639711, 2023).
tumor (continued). "The influence of EGFR overexpression on survival is obtained when 10% of EGFR+ tumor cells are used as a cut-off point, whereas cut-off points higher than 10% are not discriminative in this sense." (PMID 37569265, 2023). "Oral administration of mobocertinib once daily at doses of 30–100 mg/kg resulted in tumor regression in a mouse model of ex20ins EGFR tumors." (PMID 38201251, 2023). "For example, NSCLC patients with PD-L1 tumor proportion score (TPS) ≥ 50% seem to benefit from immunotherapy, but for those carrying EGFR-sensitive mutations and ALK rearrangements (EGFR+/ALK+), the response to immunotherapy appears to be poor." (PMID 37266427, 2023). "Tumor cell proliferation markers, such as Ki-67, tumor cell count, and the EGFR, therefore play critical roles in cancer research, either as potential treatment effect monitors or therapeutic targets." (PMID 37894447, 2023). "While EGFR kinase inhibitors (EGFR–TKIs) are widely used and efficacious in treatment, increases in resistance and tumor recurrence with alternative survival pathway activation, such as that of AXL and MET, occur frequently." (PMID 37834326, 2023). "The addition of anti-EGFR is recommended for the treatment of right-sided RAS wild-type mCRC if the goal is a reduction in tumor size." (PMID 37511664, 2023). "ERL is a tyrosine kinase inhibitor that has been found to be capable of normalizing the tumor vasculature by downregulating VEGF while inhibiting the epidermal growth factor receptor (EGFR)." (PMID 37111692, 2023). "EGFR is a transmembrane tyrosine kinase receptor involved in tumor cell proliferation, invasion, and metastatic angiogenesis." (PMID 36941614, 2023). "In this model, rare, sporadic lung epithelial cells expressing oncogenic EGFR expanded to form pre-invasive neoplasia by 10 weeks." (PMID 37020004, 2023). "Based on these findings, we concluded that the expression of CCN3 can induce EGFR-dependent tumor progression as well as EGFR activation." (PMID 36737605, 2023). "The association of BID levels with sensitivity to SAC abrogation was then extensively validated, not only in a total of 32 EGFR-mut clones but also in 21 tumor cell lines of different origins." (PMID 37443114, 2023). "It is known that the EGFR signaling pathway modulates the tumor microenvironment and that anti-EGFR therapy directly affects responses to ICI." (PMID 37370790, 2023). "EGFR is highly overexpressed on many different types of cancers and when activated can induce proliferation, migration, and invasion of tumor cells." (PMID 39086690, 2023). "GPER is a membrane estrogen receptor, which is expressed in both PCa and normal glands GPER-mediated responses have a key role in PCa, and ligand binding to GPER activates EGFR involving in the stimulation of tumor migration and invasion." (PMID 37361598, 2023). "Tumors without detectable EGFR expression responded to EGFR inhibition, implicating that EGFR blockade potentially influenced the tumor-specific immune responses." (PMID 38001917, 2023). "As a potential solution, rCBV was able to predict differences in IDH1 mutation and MGMT status, and tissue from hypercellular and hypervascular microfoci revealed greater expression of Ki‐67, HIF‐1a, CD31, and EGFR compared to tumor background." (PMID 36866773, 2023). "One of the most valuable target sites for tumor diagnosis and treatment is the human epidermal growth factor receptor (EGFR), which is a receptor tyrosine kinase regulated by more than seven activating ligands." (PMID 38067344, 2023). "Distinct phosphorylation sites in MIG6 contribute to EGFR signaling regulation, migration, invasion and tumor progression." (PMID 37834326, 2023). "Activated EGFR performs a variety of biological functions, such as functions related to tumor growth, survival, and progression." (PMID 37266143, 2023).
tumor (continued). "In another study, nanobody-albumin nanoparticles (NANAPs) were used for the delivery of 17864-Lx-a, a platinum-bound sunitinib analogue multikinase inhibitor, to EGFR overexpressing tumour cells." (PMID 36980527, 2023). "It inhibits tumor cell proliferation and promotes tumor cell apoptosis by inhibiting the transmission of the signal of epidermal growth factor receptor (EGFR) in tumor cells." (PMID 37122839, 2023). "PC1 and PC2, were extracted, they accounted cumulatively for 94.7% of the variance of the data analysed, it suggests that patient's age and histological type of tumor have significant association with CD10 and EGFR expression in BPT." (PMID 38974258, 2023). "Anti-EGFR VHHs effectively inhibit proliferation of tumor cells in vitro and outgrowth of solid tumors in vivo by blocking EGF-mediated signaling." (PMID 37746282, 2023). "With these inputs to the computational model, the individual outcomes of the virtual patients (i.e., tumor size evolution and time to progression for the In Silico EGFR mutant LUAD (ISELA) model) are simulated." (PMID 37524705, 2023). "Low levels of EGFR expression after treatment correlated with tumor regression and higher survival rates in the study, while high EGFR expression was associated with disease progression, treatment resistance, and sentinel lymph-node metastases." (PMID 36766486, 2023). "Macrophages releasing anti-EGFR antibodies effectively engulfed tumor cells expressing EGFR through antibody-dependent cell-mediated cytotoxicity." (PMID 38090576, 2023). "RAS-mutated tumours are associated with a worse prognosis than RAS and BRAF wild-type tumours, which is also due to intrinsic resistance to the anti-EGFR agents cetuximab and panitumumab." (PMID 37297026, 2023). "TGFβR-KO CAR-EGFR T-cells targeting TGFβR2 are also being investigated to enhance the anti-tumor activity of CAR T-cell therapy in EGFR-overexpressing solid tumors, though results have yet to be published (NCT04976218)." (PMID 37020537, 2023). "For instance, the epidermal growth factor receptor (EGFR) gene can differ significantly in different regions of the tumor." (PMID 38117803, 2023). "The downstream pathways of EGFR signaling not only contribute to DNA synthesis and cell proliferation but also exert an influence on the tumor microenvironment (TME)." (PMID 37759950, 2023). "Most of the GBMs and low-grade astrocytomas as well as many other types of solid cancers overexpress wild-type EGFR protein throughout the entire tumor." (PMID 37446288, 2023). "In this approach, saporin accumulated at high concentrations in cancer cells, using the tumor specificity of EGFR, and saporin exerted its enzymatic activity only in light‐irradiated cells." (PMID 36655546, 2023). "On the other hand, a case report showed that the tumor in the right parietal lobe with EGFRvIII and EGFR amplification actively progressed on osimertinib while EGFRvIII‐negative left frontal lobe tumor reached a complete response." (PMID 36622089, 2023). "IL-1β, another immune-suppressive cytokine to recruit MDSCs toward tumor sites, was observed to be strongly expressed in EGFR-positive-specific cells." (PMID 36949948, 2023). "In xenograft models, improved suppression of MAPK signaling and increased tumor regression when treated with a combination of EGFR and BRAF inhibition have been reported." (PMID 36900187, 2023). "The oncogenic mechanism linked to the constitutive activation of EGFR is relevant in oral carcinogenesis, as it occurs in other human neoplasms in which, on average, 50–70% of malignant cells overexpress EGFR." (PMID 37569265, 2023). "Panitumumab, a recombinant humanized anti-EGFR monoclonal antibody, was found to have significant tumor suppressive effects in NSCLC cell lines in an in vitro study." (PMID 36768566, 2023). "We have previously observed crosstalk between EGFR and extranuclear steroid receptors (AR and ER) in tumor cells (MCF-7 and LNCaP)." (PMID 37370896, 2023).
tumor (continued). "Our previous study has shown that the third-generation EGFR inhibitor AZD-9291 has good anti-tumor activity on GBM cells in vitro and in vivo." (PMID 38115126, 2023). "It would be interesting to determine its anti-tumor effect and adjuvant effect for EGFR-targeting therapies." (PMID 36899869, 2023). "The efficacy of complete resection based on tumor downstaging after treated with neoadjuvant EGFR-TKI therapy remains controversial for EGFRm NSCLC patients diagnosed as stage IIIB disease." (PMID 36776292, 2023). "Overexpression of the epidermal growth factor receptor (EGFR) has been shown to be a critical factor in tumor development and cancerprogression." (PMID 37808374, 2023). "We also observed that EGFR enhancer-repressed tumour spheres tend to display a reduced fusion and invasion capacity, when confronted with chick brain spheroids in 3D spheroid invasion assays." (PMID 37803333, 2023). "The molecular mechanism of vascular endothelial growth factor (VEGF) inhibitors combined with EGFR inhibitors in the treatment of NSCLC suggests synergistic anti-tumor effects and drug resistance alleviation." (PMID 37543587, 2023). "Treatment with ORIC-101 reduced tumor levels of phospho-EGFR and cyclin D1 and suppressed tumor growth in a dose-dependent manner, with 150 mg/kg resulting in a median growth inhibition of 50%." (PMID 37691854, 2023). "For example, the suppressor miRNA hsa-let-7a was used to design anti-tumor extracellular vesicles for targeting EGFR and c-Myc to repress tumor growth." (PMID 37629204, 2023). "The generation of BiTes targeting Vγ9Vδ2-T-cells, a small subset of the T-cell population, and EGFR showed T-cell activation and subsequent tumor cell lysis via secretion of inflammatory cytokines both in vitro and in vivo." (PMID 37686035, 2023). "Collectively these data lend credence to the idea that EGFR-p63-FST signaling in the complex tumor microenvironment of HNSCC modulates the immune response." (PMID 37492374, 2023). "Although the combination of osimertinib and dasatinib had anti-tumor efficacy in patients with EGFR-mutant NSCLC in the front-line setting, the treatment was limited by chronic toxicities, which were primarily due to dasatinib." (PMID 36902280, 2023). "At the plasma membrane in unpolarized epithelia during tumor progression, EGFR forms a complex with MUC1." (PMID 37720348, 2023). "Some candidate tumor antigens have been assessed as the best immunogenic antigens in anticancer phage-based vaccines, such as Epidermal Growth Factor Receptor (EGFR), Fms-like tyrosine kinase 4 (Flt4), and Melanoma Antigen Gene (MAGE)." (PMID 37809683, 2023). "Among patients with an RAS-Mut tumor, 1.1% received EGFR inhibitors and 59.7% received VEGF inhibitors and, among those with a BRAF-Mut tumor, 6.3% received EGFR inhibitors and 57.2% received VEGF inhibitors." (PMID 36656585, 2023). "Improving on these findings, 10B-enriched BPO4NPs (98.5% 10B loading) were synthesized and modified on the surface with anti-EGFR antibodies equipping them with tumor-targeting ability." (PMID 37444386, 2023). "In NIFTP, our results showed that EGFR mRNA is overexpressed while the EGFR protein expression is low with enrichment at the plasma membrane of tumor cells." (PMID 37114127, 2023). "Calcitriol has been proven to mediate the chemopreventive function of growth inhibitors and effectively enhance the inhibitory effects of erlotinib (an anti-EGFR mAb) against tumour proliferation in a patient-derived xenograft model of HNSCC." (PMID 37299554, 2023). "The objectives of the present study were to analyze our hospital’s clinical management of EGFR-mutated NSCLC patients, with a specific emphasis on how we used LB techniques, and assess the impact of LB techniques on tumor evolution and OS among patients." (PMID 37510091, 2023).